PLCB2 (phospholipase C beta 2)
Description:
The production of the second messenger molecules diacylglycerol (DAG) and inositol 1,4,5-trisphosphate (IP3) is mediated by activated phosphatidylinositol-specific phospholipase C enzymes. In neutrophils, participates in a phospholipase C-activating N-formyl peptide-activated GPCR (G protein-coupled receptor) signaling pathway by promoting RASGRP4 activation by DAG, to promote neutrophil functional responses (By similarity).
Synonyms: PLC-beta-2; FLJ38135
Tractability: Small molecule: a structure with a bound ligand is known; it has a high-quality binding pocket. Antibody: the Human Protein Atlas places it where antibodies can reach. PROTAC: ubiquitination databases record sites on it; its protein half-life has been measured.
Gene: Protein-coding gene on chromosome 15 (40,278,176 to 40,307,941, reverse strand). Ensembl gene ENSG00000137841.
Subcellular location (Human Protein Atlas): Cytosol; Basal body; Golgi apparatus; Plasma membrane
Pathways (Reactome):
Signal Transduction: Ca2+ pathway; G alpha (q) signalling events; G beta:gamma signalling through PLC beta; PLC beta mediated events
Metabolism: Acetylcholine regulates insulin secretion; Fatty Acids bound to GPR40 (FFAR1) regulate insulin secretion; Synthesis of IP3 and IP4 in the cytosol
Neuronal System: Presynaptic function of Kainate receptors
Sensory Perception: Sensory perception of sweet, bitter, and umami (glutamate) taste
Gene Ontology:
Molecular function: phosphatidylinositol phospholipase C activity; phosphatidylinositol-4,5-bisphosphate phospholipase C activity; protein binding; phospholipase C activity; calcium ion binding; G-protein beta/gamma-subunit complex binding; phospholipid binding; phosphoric diester hydrolase activity
Biological process: cell chemotaxis; phosphatidylinositol metabolic process; phospholipase C-activating G protein-coupled receptor signaling pathway; G protein-coupled receptor signaling pathway; phosphatidylinositol-mediated signaling; phospholipid metabolic process; release of sequestered calcium ion into cytosol; detection of chemical stimulus involved in sensory perception of bitter taste; intracellular signal transduction; lipid catabolic process; lipid metabolic process; signal transduction
Cellular component: cytoplasm; cytosol; G-protein beta/gamma-subunit complex; neuronal dense core vesicle
Genetic constraint (gnomAD): Loss-of-function variants: 101 observed, 123.82 expected, observed/expected ratio (o/e) 0.82, 90% interval 0.69 to 0.96. The upper end of that interval is the gene's LOEUF score, 0.96, which puts it in group 4 of 6, group 1 being the genes least tolerant of losing a copy. Missense variants: 1,312 observed, 1,442.1 expected, observed/expected ratio (o/e) 0.91, 90% interval 0.87 to 0.95. Synonymous variants: 572 observed, 551.24 expected, observed/expected ratio (o/e) 1.04, 90% interval 0.97 to 1.11.
Homologues: Orthologues: chimpanzee PLCB2 (99% identical), macaque PLCB2 (96% identical), dog PLCB2 (92% identical), pig PLCB2 (92% identical), rabbit PLCB2 (87% identical), guinea pig PLCB2 (86% identical), mouse Plcb2 (86% identical), rat Plcb2 (86% identical), tropical clawed frog plcb2 (66% identical), Drosophila melanogaster Plc21C (36% identical), Caenorhabditis elegans plc-3 (20% identical), Drosophila melanogaster sl (18% identical), and 2 more. Paralogues in human: PLCB1 (46% identical), PLCB3 (45% identical), PLCB4 (34% identical), PLCE1 (25% identical), PLCH1 (23% identical), PLCH2 (23% identical), PLCL2 (22% identical), PLCL1 (21% identical), PLCG1 (21% identical), PLCD4 (21% identical), PLCG2 (21% identical), PLCD3 (20% identical), and 2 more.
Diseases named in the same sentence as PLCB2 in open-access papers:
PLCB2 is named in the same sentence as 43 diseases in open-access papers, as found by Europe PMC text mining. Sharing a sentence is not in itself a finding about the gene and the disease. The quoted sentences say what the papers report.
breast carcinoma (11 papers, 2012 to 2025). "Using co-immunprecitation and co-immunofluorescence, we find that in both benign and aggressive breast cancer cell lines γ-synuclein and PLCβ2 are associated." (PMID 22905097, 2012). "The expression pattern is reported for the first time as a potential marker in MDS PLCB2, involved in inositol phosphate metabolism, has been narrowly linked to the poor prognosis in patients with hepatocellular carcinoma, lung cancer and mammary carcinoma." (PMID 32337851, 2020). "In addition, a tissue microarray analysis of 77 breast cancer tumor samples showed that PLCβ2 is highly expressed in breast cancer and is associated with a poor clinical outcome." (PMID 32276377, 2020). "In addition, high quantities of this protein have been narrowly linked to a poor prognosis of patients with mammary carcinoma, suggesting that PLCB2 is likely to be involved with both the growth and deterioration of the malignant phenotype." (PMID 31080817, 2019). "As an initial step in understanding the relationship between γ-synuclein and PLCβ2 in breast cancer, we determined whether these proteins associate in cells." (PMID 22905097, 2012). "PLCβ2 expression level is positively correlated with breast cancer and it promotes mitosis and migration of breast tumor cells." (PMID 26497576, 2015). "Furthermore, PLCβ2 expression correlates with the clinical outcome of breast cancer patients and in fact, PLCβ2 promotes migration and invasiveness in human breast cancer-derived cells." (PMID 32276377, 2020). "PLCb2 has been shown to be important for breast cancer cell migration." (PMID 26182292, 2015). "Over-production of PLCβ2 correlates with the severity of breast cancer." (PMID 22905097, 2012).
breast tumor (7 papers, 2012 to 2023). "PLCβ2 is absent in normal breast tissue, but is highly expressed in breast tumors where its expression is correlated with the progression and migration of the tumor." (PMID 22905097, 2012).
melanoma (5 papers, 2020 to 2025). A malignant, usually aggressive tumor composed of atypical, neoplastic melanocytes. "The downregulation of PLCB2 expression in melanoma reduces cell viability and induces apoptosis by altering the Ras/Raf/MAPK pathway." (PMID 40002717, 2025). "The study found that the reduction in PLCB2 levels significantly affected the survival of melanoma cells, resulting in enhanced apoptosis via the activation of the Ras/Raf/MAPK pathway." (PMID 38795225, 2024). "Knockdown of PLCB2 in melanoma cells activates the Ras/Raf/MAPK pathway, which in turn enhances apoptosis and inhibits cell survival." (PMID 36927770, 2023). "For instance, in melanomas, PLCB2 induces tumor cell apoptosis via RAS/RAF/MAPK pathway activation." (PMID 40002717, 2025). "Thus, PLCβ2 may promote G2/M progression of melanoma cells, an essential event in cancer evolution." (PMID 32276377, 2020).
viral infections (5 papers, 2019 to 2026). "Moreover, PLCβ2-deficient mice exhibit increased expression of proinflammatory cytokines and a higher frequency of death in response to virus infection, while the PLCβ2 activator, m-3M3FBS, protects mice from severe Coxsackie virus A 16 (CVA16) infection." (PMID 30765691, 2019). "PLCβ2-deficient mice infected with CVA16 have higher levels of proinflammatory cytokines and are more likely to succumb to virus infection." (PMID 30765691, 2019). "Since we have identified PLCβ2 as a negative regulator of proinflammatory cytokines during viral infection, we next evaluated the effect of m-3M3FBS on virus-induced immune responses." (PMID 30765691, 2019). "PLCB2 negatively regulates the proinflammatory response produced by viral infections." (PMID 33897690, 2021). "In summary, we have shown that PLCβ2 is specifically upregulated by dsRNA and virus infection." (PMID 30765691, 2019). "Thus, targeting PLCβ2 may be beneficial in the treatment of viral diseases such as HFMDs." (PMID 30765691, 2019). "Our findings indicate that PLCβ2 is a negative regulator of the virus-induced inflammatory response and treatment with a PLC activator could serve as a new therapeutic strategy for viral infections." (PMID 30765691, 2019).
Alzheimer disease (2 papers, 2017 to 2022). A progressive, neurodegenerative disease characterized by loss of function and death of nerve cells in several areas of the brain leading to loss of cognitive function such as memory and language. "Gene PLCB2 was shown to exhibit diagnostic value for hepatocellular carcinoma, PLCB2 also have an important role in the progression of Alzheimer’s disease and enriched in another neurodegenerative disorder Huntington’s disease." (PMID 35568907, 2022). "These genes include CACNA1C, LRP1, PLCB2, GRIN2A, and NMUR2, which are involved in pathways such as Alzheimer’s disease, long-term potentiation, calcium signaling, and transmission across chemical synapses." (PMID 29184056, 2017).
COVID-19 (2 papers, 2023). A disease caused by infection with severe acute respiratory syndrome coronavirus 2. "The expression of PLCβ1 and PLCβ2 was increased and downregulated, respectively, in GCs-treated COVID-19 patients." (PMID 36851787, 2023).
Ewing sarcoma (2 papers, 2000 to 2019). A small round cell tumor that lacks morphologic, immunohistochemical, and electron microscopic evidence of neuroectodermal differentiation. "As also reported, PLCB2 and PLCB3 are likely involved in the proliferation of Ewing's sarcoma cells." (PMID 31080817, 2019).
influenza (2 papers, 2022 to 2024). An acute viral infection of the respiratory tract, occurring in isolated cases, in epidemics, or in pandemics; it is caused by serologically different strains of viruses (influenzaviruses) designated A, B, and C, has a 3-day incubation period, and usually lasts for 3 to 10 days. "An apparent distinction is reduced expression of Chat and Plcb2 by post-influenza lung tuft cells." (PMID 36073526, 2022).
leukaemia (2 papers, 2016 to 2020). "Previously, we reported that in leukemia cells, WDR26 fosters the interaction between Gβγ and its effector PLCβ2 by directly binding both proteins, thereby promoting Gβγ-stimulated PLCβ2 activation and Ca2+ signaling." (PMID 26895380, 2016).
Obesity (2 papers, 2020 to 2022). Accumulation of substantial excess body fat. "The rest two genes LUZP6 and PLCB2 were not implicated earlier in obesity or related diseases." (PMID 35568907, 2022). "For the identified DEHGs for obesity, there were six previously reported genes (UGGT1, ANO6, MPEG1, PTGS1, CLU and IQGAP1) and two novel genes (LUZP6 and PLCB2) for obesity." (PMID 35568907, 2022).
renal carcinoma (2 papers, 2025). A carcinoma arising from the epithelium of the renal parenchyma or the renal pelvis. "Nine intersecting genes were screened and used to construct a prognostic model, whereby seven key biomarkers—MXD3, PLCB2, CCDC88B, DEF6, IFNG, TBC1D10C, and PLEKHN1—were significantly influenced the prognosis of renal cancer." (PMID 41357186, 2025). "We utilized Transwell assays to explore the functional role of PLCB2 in RCC cell migration and invasion, revealing that a siRNA-mediated reduction in PLCB2 significantly impairs these capabilities in renal cancer cells." (PMID 40002717, 2025).
adenoma (1 paper, 2017). A neoplasm arising from the epithelium. "For the opposite case, u(MA, HA), the gene DSPP, related to deafness and tooth abnormalities (dentin dysplasia and dentinogenesis imperfecta) were found alongside PLAG1, DCLRE1C and PLCB2 to be associated with adenomas, severe immunodeficiency and platelet deficiency respectively." (PMID 29161290, 2017).
African trypanosomiasis (1 paper, 2021). "Of the 38 African trypanosomiasis ID5143 pathway genes nine could not be detected including Kng1 and 2 encoding the kallikrein-kinin hormonal cascade in addition to Il12b and the E-selectin gene Sele while the levels Il12a, Apoa1, Fasl and Plcb2 message were subthreshold." (PMID 34762691, 2021).
atherosclerosis (1 paper, 2022). A disease characterized by the build-up of fatty material and calcium deposition in the arterial wall resulting in partial or complete occlusion of the arterial lumen. "PLCB2 expression is regulated by NF-κB and is involved in platelet activation, inflammation, and atherosclerosis." (PMID 35203642, 2022). "The involvement of PLCB2 in inflammation and atherosclerosis and its increased expression in AVF FA indicates the role of PLCB2 in vessel thrombosis and probably early AVF failure." (PMID 35203642, 2022).
Crohn disease (1 paper, 2013). A gastrointestinal disorder characterized by chronic inflammation involving all layers of the intestinal wall, noncaseating granulomas affecting the intestinal wall and regional lymph nodes, and transmural fibrosis. "Five genes (NME6 from the purine/thiopurine network, PLCB2 of the RAC1 network, and HVCN1, CTSS, and DEF8) correlated with the Harvey-Bradshaw index of Crohn’s disease activity." (PMID 23437289, 2013). "The expression levels of four genes identified by microarray screening (PLCB2, HVCN1, CTSS, and DEF8) and one purine/thiopurine related gene (NME6) correlated significantly with the clinical activity of Crohn’s disease." (PMID 23437289, 2013).
depression (1 paper, 2022). "Consequently, further study is needed to understand the underlying mechanism of these DEGs (including Eps8l1, Plcb2, Mpp1, Pidd1) in Asmt-related depression and exercise effects, thus provide new targets for the treatment of exercise for depression." (PMID 35771226, 2022). "Of these, Eps8l1 and Plcb2 were the first time to be proposed as the target genes in depression." (PMID 35771226, 2022). "Our results of enrichment analysis suggested that Plcb2 may be also one of depression-related target molecules like Plcb1." (PMID 35771226, 2022). "In other words, Eps8l1 and Plcb2 may regulate synaptic plasticity by affecting the expression level of Bdnf to participate in the molecular mechanisms of depression." (PMID 35771226, 2022). "Taken together, Plcb2 may be a representative molecular marker of depression through the effects on circadian rhythm and metabolism, which are crucial for depression and exercise." (PMID 35771226, 2022). "Consistent with the PPI network, Asmt knockout may play an important role through Mtnr1b/Gna11/Plcb2/Bdnf in depression." (PMID 35771226, 2022).
diabetes (1 paper, 2018). "Our results showed that the expression of STRs and associated signaling components (Gα-gustducin, PLCβ2, and TRPM5) was obviously downregulated under the condition of diabetes in vivo and in vitro." (PMID 29675433, 2018).
endothelial dysfunction (1 paper, 2022). In vascular diseases, endothelial dysfunction is a systemic pathological state of the endothelium (the inner lining of blood vessels) and can be broadly defined as an imbalance between vasodilating and vasoconstricting substances produced by (or acting on) the endothelium. "Specifically, we identified CCRL2, LGALS9, and PLCB2 as key genes associated with abnormal ESS and AS and initially explored the roles of these genes in endothelial dysfunction and AS, thus highlighting the possibility of new preventive and therapeutic strategies for AS by targeting these genes." (PMID 35990248, 2022).
glomerulopathies (1 paper, 2022). "Plcb2 is up-regulated in DN patients only, whereas Col3a is up-regulated in all investigated glomerulopathies." (PMID 35652093, 2022).
liver cirrhosis (1 paper, 2014). "Additionally, PLCB2 expression was upregulated in the cytoplasm of the activated LX-2 cells, as well as in the hepatocytes and sinusoidal cells of liver cirrhosis tissues." (PMID 25460309, 2014).
muscular dystrophy (1 paper, 2016). Muscular dystrophy (MD) refers to a group of more than 30 genetic diseases characterized by progressive weakness and degeneration of the skeletal muscles that control movement. "Notably, PLCB2 was recently shown to regulate calcium influx into skeletal muscle, and this regulation was abrogated in muscular dystrophy." (PMID 27099343, 2016).
tumor (14 papers, 2000 to 2025). "Phospholipase C beta 2 (PLCB2) is a phosphatidyl C family member, which is generally considered to be a gene associated with tumor immune response." (PMID 40337271, 2025). "In summary, our study demonstrates that elevated PLCB2 expression in RCC significantly promotes tumor cell proliferation, EMT, and enhanced invasiveness." (PMID 40002717, 2025). "Recent studies show that PLCB2 plays significant roles in various tumor types." (PMID 40002717, 2025). "PLCβ2 expression correlated with tumor size, proliferation index and tumor grade." (PMID 32276377, 2020). "In conclusion, our study identifies PLCB2 as a significant regulator of EMT in RCC through its activation of the PI3K/AKT pathway, thereby promoting tumor invasion and metastasis." (PMID 40002717, 2025). "The results showed that, with the exception of SMIM24, which was highly expressed in normal tissues, PLCB2, HLA-DQB2, IFNG, and XCR1 were all highly expressed in tumor tissues." (PMID 39273185, 2024). "AASEs of tumor-related genes, such as DDX17, PLCB2, and SEMA6C had higher inclusion levels in G2." (PMID 35989380, 2022). "As a result, we found that ITPR1, ITPR2, and ITPR3 proteins may interact with tumor-promoting genes, such as PLCB1, PLCB2, PRKCA, and RGS21, which may partially explain its oncogene roles." (PMID 35580861, 2022). "Like γ-synuclein, phospholipase C β2 (PLCβ2) is absent in normal breast tissue, but is highly expressed in transformed tissue where its level of expression is directly related to tumor progression and migration presumably through its regulation by small G proteins." (PMID 22905097, 2012). "Although PLCB2 has not been widely studied in RCC, emerging evidence indicates its oncogenic relevance in several tumor types." (PMID 40002717, 2025).
cancer (9 papers, 2013 to 2025). A tumor composed of atypical neoplastic, often pleomorphic cells that invade other tissues. "Among the myriads of molecular players in cancer biology, phospholipase C Beta 2 (PLCB2), a member of the phospholipase C family, located on chromosome 4, has emerged as a potential candidate in cancer progression." (PMID 40002717, 2025). "PLCB2 belongs to the phospholipase C beta (PLCB) gene family, which has been identified to play an important role in the development of various cancers." (PMID 38023248, 2023).
infection (3 papers, 2019 to 2024). The state of being infected such as from the introduction of a foreign agent such as serum, vaccine, antigenic substance or organism. "As Plcb2−/− mice had significantly higher mRNA levels of Tnf, Il6 and Il12 and little changed viral loads compared with wild-type mice after CVA16 infection, we next monitored the survival and histopathological pathogenesis of mice challenged with CVA16." (PMID 30765691, 2019).
immune dysfunction (2 papers, 2017 to 2025). "Furthermore, given PLCB2’s widespread involvement in neural signaling and immune regulation, systemic inhibition may lead to adverse effects such as neurotoxicity or immune dysfunction." (PMID 40002717, 2025).
adenocarcinoma (1 paper, 2019). A common cancer characterized by the presence of malignant glandular cells. "High mRNA expression levels of PLCB1, PLCB2, and PLCB3 were significantly associated with poor overall survival (OS) of all NSCLC patients and significantly associated with poor prognosis of adenocarcinoma." (PMID 31080817, 2019).
PLCB2 also shares sentences with these, for which no sentence is quoted: hepatocellular carcinoma (2 papers); lung carcinoma (2); autoimmune disease (1); bacterial infection (1); basal cell carcinoma (1); colitis (1); deafness (1); dentin dysplasia (1); dentinogenesis imperfecta (1); glioma (1); Huntington disease (1); Hyperglycemia (1); Immunodeficiency (1); Insulin resistance (1); myeloid leukemia (1); renal cell carcinoma (1); viral diseases (1).